CD4 (CD4 molecule)
Diseases named in the same sentence as CD4 in open-access papers (continued):
Sharing a sentence is not in itself a finding about the gene and the disease.
Infertility (15 papers, 2009 to 2025). "During embryo implantation, the maternal immune system is comprised of a unique imbalance of subtypes of T lymphocytes (CD4+ T cells and killer T cells) which are emerging as a prevalent cause of infertility." (PMID 38645487, 2024). "A recent cross-sectional study found lower serum CD8 T cell levels in infertile patients compared to controls and another identified T% and CD4+ T% as independent risk factors for PCOS." (PMID 38254716, 2024). "APCs then expanded both CD4+ and CD8+ T cell populations and caused significantly more infertility in female mice infected with non‐opsonized Chlamydia." (PMID 38441219, 2023). "Modulation of cytokines and transcription factors (T-bet and GATA-3) in CD4 enriched cervical cells of Chlamydia trachomatis infected fertile and infertile women upon stimulation with chlamydial inclusion membrane proteins B and C was reported." (PMID 32413046, 2020). "Our results indicated that the expression of PD-1 in FF CD4+ or CD8+ T cells from the PCOS group with infertility was significantly higher than that from the control group (P < 0.05)." (PMID 30988342, 2019). "The expression of PD-1 on CD4+ T cells in the PCOS group with infertility was significantly higher than that in the control group (13.80% ± 3.18% vs. 26.13% ± 3.31%, P < 0.05; 10.31% ± 2.34% vs. 19.30% ± 2.50%, P < 0.01)." (PMID 30988342, 2019). "We detected high levels of IL-12 and IL-23 in IncB or IncC-stimulated CD4+ T cells from CT-positive fertile women compared to CT-positive infertile women and controls." (PMID 19698128, 2009). "Significantly high levels of TNF-α and IL-6 levels were secreted in CD4+ T cells from CT-positive fertile and infertile women compared to controls." (PMID 19698128, 2009). "In this study we found elevated expression of transcription factor T-Bet in Inc- stimulated CD4+ T cells from CT-positive fertile and infertile women compared to controls." (PMID 19698128, 2009). "Significantly higher levels of IL-1β, IL-6 and IL-10 were secreted from IncB or IncC stimulated CD4+ T cells obtained from CT-positive infertile women as compared to CT-positive fertile women or controls (P < 0.05)." (PMID 19698128, 2009). "Further in another report, a high percentage of plasmocytoid DCs in cervical secretions of CT-positive infertile women has suggested a possible mechanism recognition of CD4 or CD8 antigens on antigen presenting cells such as DCs." (PMID 19698128, 2009). "Elevated expression of GATA3 transcription factor was detected in Inc stimulated CD4+ T cells from CT-positive infertile women compared to CT-positive fertile women and controls." (PMID 19698128, 2009). "In this study we detected high levels of IL-1β, IL-6, IL-4, IL-5 and IL-10 in IncB or IncC-stimulated CD4+ T cells in CT-positive infertile women compared to CT-positive fertile women and controls." (PMID 19698128, 2009). "Emerging data shows involvement of Inc stimulated CD4 positive T cells in aiding host immunity in infected fertile and infertile women through the secretion of interferon gamma." (PMID 19698128, 2009). "This study aimed to investigate the maternal immunophenotyping profile (percentage of Natural Killer [NK] cells and the CD4/CD8 [cluster designation] ratio in peripheral blood lymphocytes) and the HLA (Human Leukocyte Antigen)-DQA1 alleles sharing in infertile couples." (PMID 36968684, 2023). "Furthermore, an inverse correlation between the expression of PD-1 and IFN-γ in FF CD4+ or CD8+ T cells was found in infertile patients with PCOS (P < 0.05)." (PMID 30988342, 2019). "Significant higher expression (P < 0.05) of Interferon-gamma, IL-12, IL-23 and GM-CSF were found in Inc-stimulated CD4 enriched cervical cells of CT-positive fertile women and contrastingly high IL-1 Beta, IL-4, IL-5, IL-6 and IL-10 levels were found in CT-positive infertile women." (PMID 19698128, 2009).
Infertility (continued). "Thus higher expression of T-Bet in CT-positive fertile women compared to CT-positive infertile women is indicative of differentiation of native Th0 cells towards a CD4+-Th1 mediated protective response for clearance of CT." (PMID 19698128, 2009). "Our results showed that the PD-1 expression on CD4+ or CD8+ T cells, which reflects T cell exhaust, positively correlated with the serum E2 level in the infertile patients with PCOS (r2 = 0.424, P < 0.05 and r2 = 0.431, P < 0.05, respectively)." (PMID 30988342, 2019). "In summary, this report found that increased expression of PD-1 and significantly decreased expression of IFN-γ were detected in CD4+ T and CD8+ T cells in infertile patients with PCOS (P < 0.05)." (PMID 30988342, 2019). "IncB or IncC-stimulated CD4+ T cells from CT-positive fertile women produced IFN-γ and GM-CSF at levels higher than in CT-positive infertile women and controls." (PMID 19698128, 2009). "In contrast, IncB and IncC stimulated CD4+ T cells obtained from CT-positive fertile women secreted significantly higher levels of IL-12, IFN-γ, GM-CSF and IL-23 compared to CT-positive infertile women or controls (P < 0.05)." (PMID 19698128, 2009). "Evidence suggests that CD4 and CD8 proportions are altered in women with infertility." (PMID 36968684, 2023). "Interestingly, inverse correlations between the expressions of PD-1 and IFN-γ in the FF CD4+ and CD8+ T cells were found in the infertile patients with PCOS (r2 = 0.418, P < 0.05 and r2 = 0.387, P < 0.05, respectively)." (PMID 30988342, 2019). "Although the percentage of CD4+ T cells did not change in PCOS patients with infertility, both CD4+ and CD8+ T cells expressed significantly lower levels of CD69 in the PCOS group (P < 0.01)." (PMID 30988342, 2019). "Furthermore, the levels of CD69 and IFN-γ were significantly decreased and the level of PD-1 was increased in both CD4+ and CD8+ T cells from infertile patients with PCOS (P < 0.05)." (PMID 30988342, 2019). "We speculate that the higher expression of PD-1 in CD4+ T and CD8+ T cells in the FF in PCOS patients with infertility probably cannot induce T cell activation or recruitment, which, in turn, leads to the failure of dominant follicle selection and development." (PMID 30988342, 2019). "On stimulation of CD4+ T cells with IncB or IncC, IFN-γ and T-Bet levels were found to be positively correlated in CT-positive fertile women whereas IL-4 mRNA levels were positively correlated to GATA3 expression in CT-positive infertile women." (PMID 19698128, 2009). "On stimulation of CD4+ T cells with IncB or IncC, significant increase in mRNA expression levels of IFN-γ, IL-12, GM-CSF (P < 0.05) was observed in cells obtained from CT-positive fertile women compared to controls and CT-positive infertile women." (PMID 19698128, 2009). "However, dysfunction or overactivation of T cells (CD3, CD4, CD8), B cells (CD20), and macrophages (CD68) can disrupt endometrial immune homeostasis, triggering chronic inflammation and impairing embryo implantation, ultimately leading to infertility." (PMID 40375897, 2025). "Moreover, the expression of PD-1 on CD4+ or CD8+ T cells was positively correlated with the estradiol (E2) levels in the serum and reversely correlated with the expression of IFN-γ in CD4+ or CD8+ T cells in infertile patients with PCOS." (PMID 30988342, 2019).
lentivirus infection (15 papers, 2008 to 2025). Virus diseases caused by the Lentivirus genus. "Acute lentivirus infections are characterized by high levels of viremia coupled to a dramatic loss of CD4+ T cells in the GI tract." (PMID 25503264, 2014). "We conclude that CD4 was originally permissive to primate lentiviruses, but that selective pressures exerted by SIVs in the chimpanzee and gorilla lineages led to the retention of mutations that now confer resistance to primate lentivirus infection." (PMID 38014262, 2024). "Human peripheral blood T lymphocytes were induced into CD4+ T cells, followed by lentivirus infection and daphnetin treatment." (PMID 41462398, 2025). "Following lentivirus infection, naïve CD4+ T cells were subjected to Th2 polarization conditions, and we observed the decreased STEAP4 protein expression in Th2 cells with STEAP4 knockdown." (PMID 41422349, 2025). "The expression of GARP is a marker for activated Tregs, and GARP+CD4+CD25+ cells are increased in blood during chronic lentivirus infections." (PMID 36016413, 2022). "Several mechanisms have been proposed to account for the down-regulation of CD4 following primate lentivirus infection." (PMID 18190699, 2008). "Subsequently, STEAP4 knockdown in naïve CD4+ T cells was mediated by lentivirus infection." (PMID 41422349, 2025). "In the case of lentivirus infection, where both Treg and Th cells are chronically activated, maintenance of CD4+CD25+ Treg numbers and function may be favored at the expense of the Th cell pool." (PMID 24438223, 2014). "Following lentivirus infection and stable strain selection, the transgene was expressed on the cell membrane, enabling purified exosomes to specifically recognize mouse CD4+ T cells through the variable regions of the heavy and light chains and bind to CD4 molecules." (PMID 40284659, 2025). "While lentivirus infection resulted in a higher percentage of CAR+ cells among CD4+ cells than among CD8+ cells, integration was unbiased between CD4+ and CD8+ cells by the electroporation strategy." (PMID 36045296, 2022). "Many reports suggest that during the course of lentivirus infection the percentage of CD4+CD25+ cells among the CD4+ fraction remains stable, particularly in lymphoid organs, despite the overall decline in CD4+ cell numbers." (PMID 24438223, 2014). "Collectively, these data provide one of the most comprehensive evaluations of SIV-induced changes in oral microbiome and CD4 + T cell populations, and also suggest that oral PBX may have some anti-inflammatory properties in lentivirus infections." (PMID 34267278, 2021).
Lyme disease (15 papers, 2006 to 2024). Lyme disease (named after the towns in the USA where the disease was first identified) is a bacterial infection caused by Borrelia burgdorferi. "We specifically chose to compare Treg PD-1 expression to that of T-bet+ Th1 CD4+ T cells, which have been strongly implicated in Lyme disease pathogenesis." (PMID 36265003, 2022). "The individual with neuroborreliosis had 320 blood CD4+ T-cells per μL, closer to the range of the four HZ escape cases." (PMID 32697807, 2020). "Levels of CXCR3+ CD4 T cells were determined by polychromatic flow cytometry, and found to be significantly lower in the blood of patients with acute Lyme disease versus controls." (PMID 24740099, 2014). "Case 2 had a low CD4+ count with progression to neuroborreliosis, despite treatment for his recent early LB." (PMID 21118561, 2010). "Indeed, it has been postulated that CXCL-10 creates a chemokine gradient between the CSF and serum and recruits CD4+ T-cells into the CSF of patients with neuroborreliosis." (PMID 23883071, 2013). "More importantly, the present study demonstrated that feeding 1.1% scFOS+ to healthy senior dogs increased the CD4+:CD8+ T-cell (Helper:Cytotoxic T cell) ratio (p < 0.001) during and after vaccination against Lyme disease." (PMID 39634761, 2024). "High CCR5 expression has been observed on csf CD4+ and CD8+ lymphocytes in neuroborreliosis, where it was also co-expressed with CXCR3." (PMID 26906062, 2016). "The inflammatory infiltrate in both the early and late skin manifestations of Lyme borreliosis is mainly composed of CD68+ macrophages and CD45RO+ memory T cells, with a predominance of CD4+ helper T cells." (PMID 16495924, 2006). "Interestingly, in non-autoimmune driven joint inflammation, such as injury or Lyme disease, composition consists of more CD4+ compared to CD8+ T cells, the inverse of what we see here in autoimmune inflammation." (PMID 39101538, 2024). "MICA is also a ligand for NKG2D on γδ T cells, which have been shown to increase neutralizing antibodies in the absence of CD4 αβ T cells against vesicular stomatitis virus (VSV), foot-and-mouth disease virus, as well as Borrelia burgdorferi, the causative agent for lyme disease." (PMID 23372753, 2013).
metastatic carcinoma (15 papers, 2011 to 2026). A carcinoma which has spread from the original site of growth to another anatomic site. "Using a highly sensitive in vitro stimulation and cell enrichment of peripheral memory T cells from six metastatic cancer patients, we identified and isolated CD4+, and CD8+ memory T cells targeting the mutated KRASG12D and KRASG12V variants, respectively, in three patients." (PMID 30683863, 2019). "Furthermore, CD4+ T-cells in the pleural fluid of patients with either metastatic carcinomas or benign pleural lesions associated with asbestos exposure tended to be relatively more abundant than in MPM patients." (PMID 23816056, 2013). "For example, B and CTL cells were concentrated in the microenvironment of primary cancer cells, whereas CD4+ T cells and CAFs were found in the microenvironment of metastatic cancer cells." (PMID 34790166, 2021). "Several studies argued the unfavorable involvement of circulating regulatory T cells (Tregs) in cancer progression, demonstrating the presence of increased numbers of CD4+CD25highFoxP3+ especially in metastatic cancers." (PMID 22112244, 2011). "Moreover, adoptive CD4+ T cell therapy using HLA-DPB1*0401 restricted TCR recognizing MAGEA3 has been proved to be effective in 17 patients with metastatic cancer and 4/17 patients treated with DPB1*0401 restricted TCR-T cells showed durable clinical response (1CR, 3PR)." (PMID 37287989, 2023). "In total, 32.8% of patients were immunocompromised (n = 58/177; ie, with ongoing immunosuppressive therapy or with ongoing chemo-/radio-/corticotherapy, or with hemopathy, metastatic cancer, or HIV+ with CD4 lymphocytes <500/mm3 at inclusion)." (PMID 38390458, 2024). "The Class II MHC Transactivator (CIITA) is an MHC II trans-activating factor supporting CD4 + T-Lymphocyte recruitment; thus, the downregulation of CIITA was reported to be related to aggressive and metastatic carcinoma." (PMID 36831458, 2023). "Immune-suppressive CD4+CD25+FoxP3+ T-reg accumulate in primary and metastatic cancers and can prevent treatment-induced immune responses, therefore T-reg depletion represents a promising therapeutic approach." (PMID 25034887, 2014). "Moreover, since the coexistence of tuberculous lymphadenitis and metastatic carcinoma within the same regional lymph nodes was not suspected preoperatively, routine CD4+ cell count testing was not performed." (PMID 41486570, 2026).
nosocomial infection (15 papers, 2009 to 2025). An infection acquired in a hospital or other healthcare setting. "In this cohort of critically ill children with septic shock, early adaptive immune suppression, as measured by reduced CD4+ T-cell cytokine-production capacity was associated with the development of persistent or nosocomial infection." (PMID 25005517, 2014). "An increased percentage of BTLA+CD4+ T lymphocytes in critically ill patients was associated with an increased incidence of subsequent nosocomial infections and a longer hospital length of stay." (PMID 24289156, 2013). "We designed a prospective, observational study to test the hypothesis that suppressed adaptive immune function, measured with ex vivo CD4+ T-cell cytokine production capacity, would be associated with the development of persistent or nosocomial infection in children with septic shock." (PMID 25005517, 2014). "We further hypothesized that septic shock children would have increased percentage of Treg among CD4+ T cells compared with healthy children, and that among septic shock children, an increased percentage of Treg would be associated with the development of persistent or nosocomial infection." (PMID 25005517, 2014). "This study explored the related risk factors of nosocomial infection and the predictive value of human immunology-related indicators such as T lymphocyte subtypes CD3+CD4+ and CD3+CD8+ and NK cells (natural killer cells) on the occurrence of nosocomial infection." (PMID 40313971, 2025). "Moreover, the non-septic patients with CD4+ T-cells that were greater than 80% BTLA+ were more susceptible to developing nosocomial infections." (PMID 24289156, 2013). "We therefore investigated whether or not the observed increase in the percentage of BTLA+CD4+ lymphocytes in the critically ill patients associated with the development of a subsequent nosocomial infection and an increased hospital length of stay." (PMID 24289156, 2013). "The CD3+CD4+ and CD3+CD8+ cells were protective factors against nosocomial infection in patients, and their OR values and 95% CI were 0.851 (0.790–0.916) and 0.832 (0.711–0.973), respectively, p < 0.05." (PMID 40313971, 2025). "Recent research has indicated that the CD4/CD8 ratio can predict the occurrence of surgical site infection in fractures with impaired immune function and is correlated with the incidence of nosocomial infection." (PMID 40313971, 2025). "The levels of CD3+CD4+ and CD3+CD8+ cells in the peripheral blood of nosocomial infection patients decreased, indicating that the number of active cells was insufficient to participate in the cellular immune response." (PMID 40313971, 2025). "The decreased levels of CD3+CD4+ and CD3+CD8+ T lymphocyte subsets indicate that the cellular immune function of nosocomial infection patients is low." (PMID 40313971, 2025). "Transient depletion of CD4+ T cells did not lead to nosocomial infections, although follow-up periods in this study were relatively short." (PMID 31340866, 2019). "With regard to the SIRS patients, we found that those patients who developed a subsequent nosocomial infection had a significantly higher percentage of BTLA+CD4+ lymphocytes than the SIRS patients who did not develop later infections." (PMID 24289156, 2013). "An increased BTLA+ CD4+ lymphocyte frequency in the observed critically ill non-septic patients was associated with a subsequent infection; therefore, BTLA may act as a biomarker to help determine nosocomial infection development." (PMID 24289156, 2013).
peripheral T-cell lymphoma (15 papers, 2006 to 2025). "CD4 is universally expressed in peripheral T-cell lymphoma cells." (PMID 37108359, 2023). "RNA seq of CD4+, CD8+, and CD4−CD8− peripheral T-cell lymphomas (PCTL) showed that while CD4+ tumors had a consistent gene expression profile that included upregulation of GATA3 and PI3K/AKT/mTOR signaling and downregulation of PTEN, CD8+ and CD4−CD8− tumors were more heterogeneous." (PMID 41012800, 2025). "A open-label, exploratory trial to explore the efficacy in patients with biopsy proven CD4+ peripheral T cell lymphoma of non-cutaneous type who were treatment-refractory or had relapsed." (PMID 18702090, 2008). "Patients with peripheral T-cell lymphoma, not otherwise specified, most commonly have a CD4+/CD8- phenotype, with only a few being CD4/CD8 +/+ or −/−, demonstrating the potential of anti-CD4 CAR-T cells." (PMID 36261831, 2022). "The tumour cells were CD4+, CD5+ but lacked EMA, TIA-1, CD56 and EBV expression and the diagnosis was a CD30+ peripheral T-cell lymphoma unspecified." (PMID 16623775, 2006). "An ultrasound-guided biopsy of an omental implant was performed, revealing large atypical lymphoid cells positive for CD3, CD2, and CD4, and negative for CD5, CD7, and CD8, with a Ki-67 proliferation index of 90%, consistent with an aggressive peripheral T-cell lymphoma." (PMID 40761963, 2025).